BACH1 (BACH transcriptional regulator 1)
Diseases named in the same sentence as BACH1 in open-access papers (continued):
Sharing a sentence is not in itself a finding about the gene and the disease.
lung cancer (continued). "BACH1 expression in tumors are mainly due to genetic amplification as validated in breast cancer or increased protein stability as validated in lung cancer." (PMID 33809182, 2021). "In contrast, NRF2 knockdown in H23 cells delayed cell migration and invasion, which is consistent with previous studies showing that downregulation of BACH1 inhibits lung cancer metastasis." (PMID 33299528, 2020). "In two new studies on lung cancer, it was shown that therapeutic intervention that either destabilizes BACH1 or disrupts its ability to induce glycolysis have the potential to inhibit BACH1 pro-metastatic activity." (PMID 32132179, 2020). "They found that Nrf2 overexpression in lung cancer promotes the stabilization of Bach1 by inducing HO1, the enzyme catabolizing heme." (PMID 33324555, 2020). "The recent lines of evidence revealed that NRF2 inhibits the heme- and Fbxo22-mediated degradation of Bach1 by inducing Ho1, and activates the lung cancer metastasis." (PMID 31884422, 2019). "A similar decrease of HO-1 expression by Bach1 is observed in rat fibroblasts and human lung cancer cells exposed to cigarette smoke condensate in a previous study." (PMID 26925775, 2016). "A well-characterised role for BACH1 in lung cancer cells is its pro-invasive effect." (PMID 40716152, 2025). "To address the functional relevance of the BACH1 degradation observed upon paeoniflorin treatment, we tested the effect of paeoniflorin in a model of lung cancer invasion using a 3D spheroid collagen invasion assay that measures how cancer cells sprout and invade their surrounding matrix." (PMID 40716152, 2025). "While FBXO22 was shown to promote heme-induced degradation of BACH1 in lung cancer cells, the detailed mechanism of their interaction remains unclear." (PMID 39758820, 2025). "BACH1 mediates angiogenesis in an HIF1α‐independent way in lung cancer cells." (PMID 39887888, 2025). "Furthermore, HTRA3 restricts lung cancer cell migration and invasion further supporting the new link we established between the reduced migration observed in BACH1-depleted cells and HTRA3 upregulation." (PMID 40716152, 2025). "To test whether the anti-invasive effect of paeoniflorin depends on the degradation of BACH1 via FBXO22, we repeated the invasion experiments with paeoniflorin in both FBXO22-proficient and -deficient lung cancer cells." (PMID 40716152, 2025). "As BACH1 depletion/inhibition leads to reduced lung cancer cell migration we investigated whether induction of the signature genes was causally linked to the reduced migration in BACH1-KO cells." (PMID 40716152, 2025). "These authors suggested that targeting BACH1 or proteins inhibited lung cancer metastasis." (PMID 40278414, 2025). "Studies of KRASMut lung cancer models reveal that prolonged antioxidant administration (N-acetylcysteine and vitamin E) promotes metastatic progression by reducing intracellular heme availability, which subsequently stabilizes the BACH1 transcription factor." (PMID 40507333, 2025). "Importantly, this signature correlates with BACH1 basal levels in lung cancer, PDAC and melanoma cells, highlighting its relevance as a surrogate for BACH1 activity." (PMID 40716152, 2025). "This signature is sensitive (responds to both genetic and pharmacological perturbation) and specific for BACH1 (does not respond to NRF2 modulation) and can be used to provide further insight into the pro-metastatic role of BACH1 in lung cancer cells and as a tool to identify new BACH1 inhibitors." (PMID 40716152, 2025). "High level of BACH1 makes tumors more sensitive to anti-angiogenesis therapies in lung cancer." (PMID 40563308, 2025). "The relevance of BACH1 in lung cancer has been clearly demonstrated; however, to deepen our understanding of BACH1's biology and its links to lung cancer metastasis, a clear understanding of the genes and pathways regulated by BACH1 in human lung cancer cells is still necessary." (PMID 40716152, 2025).
lung cancer (continued). "In addition to its relevance as a tool to identify/validate BACH1 inhibitors, we used the information obtained from integrating our RNA-Seq and ChIP-Seq to obtain further insight into the biology of BACH1 in lung cancer." (PMID 40716152, 2025). "As BACH1 has been involved in various processes including oxidative stress responses, heme and iron homeostasis, metabolism and cell migration/invasion, an understanding of the genes and pathways regulated by BACH1 in lung cancer cells is crucial to clarify its context dependent role." (PMID 40716152, 2025). "Moreover, BACH1 expression seems to be positively associated with PFKFB3 and SLC16A1 expression according to an analysis of human lung cancer datasets." (PMID 38321558, 2024). "In addition, CDDO-trifluoromethyl-amide (CDDO-TFEA) and CDDO-Bardoxolone-Methyl (CDDO-Me) both decrease the nuclear levels of BACH1 to reduce invasion of lung cancer cells." (PMID 38321558, 2024). "Future studies should focus on defining the impact of Bach1 inactivation on endogenous malignant melanoma development and metastasis, for example in BPT mice, and compare underlying mechanisms and signaling pathways with those identified in lung cancer." (PMID 36774779, 2023). "Additionally, BACH1 regulates the self-renewal and pluripotency of embryonic stem cells and maintains the characteristics of lung cancer stem cells." (PMID 36670112, 2023). "Similar studies revealed that administering ROS-lowering doses of NAC in the drinking water or VitE in the food accelerates metastasis rates in mice with KRASG12D-induced lung cancer; this effect is mediated by the redox-sensitive transcription factor BACH1 (BTB domain and CNC homolog 1)." (PMID 36774779, 2023). "Conversely, BACH1 has been shown to activate the transcription of glycolytic enzymes, leading to increased glucose uptake, glycolysis rates, and lactate secretion, thereby promoting the glycolysis-dependent metastasis of both mouse and human lung cancer cells." (PMID 37507910, 2023). "BACH1 is stabilized by lowering ROS levels; consequently, angiogenesis gene expression in lung cancer cells, tumor organoids, and xenograft tumors increased substantially following administration of vitamins C and E and N-acetylcysteine in a BACH1-dependent fashion under normoxia." (PMID 37651203, 2023). "Subsequently, BACH1 activates transcription factors involved in the triggering process of glycolysis playing an important role in tumor growth promotion, metastasis, and chemoresistance in mouse and human lung cancer cells." (PMID 37597078, 2023). "As expected from previous studies in lung cancer cells, Bach1 deficiency did not influence mouse survival, but substantially reduced metastasis to lymph nodes and liver." (PMID 36774779, 2023). "Future studies should be able to address the efficacy of this approach in a clinical setting and could potentially extend beyond lung cancer, as we also observed correlations between BACH1 and angiogenesis gene expression in breast and kidney cancer." (PMID 37651203, 2023). "We firstly confirmed the vital role of BACH1 in the prognosis of early-stage lung cancer." (PMID 35035660, 2022). "Recent researches showed the vital role of BACH1 in promoting the metastasis of lung cancer." (PMID 35035660, 2022). "NRF2 accumulation in lung cancer stabilizes Bach1 by inducing HO1, an enzyme that breaks down heme." (PMID 35770119, 2022). "Moreover, Nrf2 released by Keap1 deactivation induced lung cancer metastases through suppression of Bach1 (another pivotal regulator of EMT) degradation in a Ho-1-dependent manner, so targeting Ho-1 or Nrf2 blockade can decrease lung cancer metastases." (PMID 35906617, 2022).
lung cancer (continued). "For example, in lung cancer, BACH1 activates the transcription of Hexokinase 2 and GAPDH, enhances the uptake of glucose of cancer cells, improves the glycolysis, and alleviates oxidative stress-induced damage of cancer cells, hence facilitating cancer cell metastasis." (PMID 34191748, 2021). "Furthermore, the increase of mitochondrial ROS (mtROS) and CSC-marker expression induced by CIH exposure was abolished in Bach1 shRNA-treated lung cancer cells." (PMID 33596919, 2021). "Now, many evidences have confirmed that Nrf2 activation could inhibit the degradation of Bach1, and then promote the progress of lung cancer." (PMID 34178646, 2021). "Two recent studies illustrated the importance of BACH1 stabilization in lung cancer metastasis." (PMID 34439295, 2021). "In addition, we would further check the detailed mechanism that Bach1 induces lung tumor growth and reduces lung cancer cell death." (PMID 34949193, 2021). "Nrf2 was shown to suppress the Fbxo22-mediated degradation of Bach1 in a heme oxygenase-1 dependent manner, suggesting that inhibition of heme oxygenase-1 could be an effective therapeutic strategy for preventing lung cancer metastasis." (PMID 34631760, 2021). "Likewise, blockade of Bach1 target genes involved in the glycolysis pathways significantly reduced metastasis phenotypes in lung cancer." (PMID 33809182, 2021). "Taken all, BACH1 mediates activation of aerobic glycolysis pathways and the metastatic process of lung cancer cells, as inhibition of BACH1 using either shRNA, sgRNA, or hemin treatment decreases migration and metastasis of cancer cells through aerobic glycolysis reduction." (PMID 33809182, 2021). "In addition, BACH1 is not only necessary but also sufficient to increase glycolysis in lung cancer cells and to promote their migration and invasion." (PMID 33499022, 2021). "Bach1 has been identified to contribute to several tumor progression, including lung cancer." (PMID 34949193, 2021). "Stabilized BACH1 as a major driver facilitated metastasis of lung cancer cells." (PMID 33809182, 2021). "Aberrant expression of BACH1 contributes to tumor metastasis in breast cancer, colorectal cancer, prostate cancer, ovarian cancer, pancreatic cancer, osteosarcoma, and lung cancer." (PMID 33932125, 2021). "Moreover, hexokinase 2 (HK2) and glyceraldehyde-3-phosphate dehydrogenase (GAPDH) have been identified among the strongest transcriptional targets of BACH1, suggesting that BACH1 stimulates glycolysis in lung cancer." (PMID 33499022, 2021). "Notably, the transcription factor BTB and CNC homology 1 (Bach1), a key factor in responding to conditions of oxidative stress, is increased in lung cancer after CIH exposure in vitro and in vivo." (PMID 33596919, 2021). "In this study, we investigated the role of Bach1 in lung cancer." (PMID 34949193, 2021). "Inhibition of Bach1 target gene, HMOX1, or Bach1-ligase overexpression could reduce Bach1-driven metastasis of lung cancer." (PMID 33809182, 2021). "BACH1 promotes metastasis in non–small-cell lung cancer by promoting cell migration and invasion." (PMID 34339740, 2021). "The association of BACH1 and NRF2 was shown to promote lung cancer metastasis." (PMID 33228209, 2020). "In addition, recent evidence suggests that in mouse models of lung cancers, activated Nrf2 inhibits the Fbxo22-dependent degradation of Bach1 via induction of Ho-1 expression, and high levels of Bach1 promoting metastasis." (PMID 32576270, 2020). "Building upon our previous findings, which identified PRC1 as a risk factor in lung cancer with low DNA methylation level, this study demonstrates that TET2 is responsible for the demethylation and transcriptional activation of PRC1 in NSCLC cells by interacting with BACH1." (PMID 40665337, 2025).
lung cancer (continued). "Notably, BACH1 regulates aerobic glycolysis to promote tumor growth, progression, and metastasis in breast cancer, lung cancer, hepatocellular cancer, and glioma by controlling the expression of genes encoding the mitochondrial electron transport chain (ETC) and glycolytic enzymes." (PMID 38321558, 2024). "Moreover, Bach1 was also involved in cell cycle, immunity, and has been shown to suppress angiogenesis and promoted cancer metastasis, such as breast, ovarian, and lung cancer." (PMID 33596919, 2021). "However, the effects of CIH on CSCs and its possible role in tumor metastatic phenotype are unknown and the role of Bach1 plays in CIH-promoted lung cancer is unclear." (PMID 33596919, 2021). "Interestingly, while mitochondrial heme promotes lung cancer proliferation and metastasis through elevating OXPHOS and promoting angiogenesis, HO-1 regulated heme seems to play a positive role in the inhibition of lung cancer metastasis through inhibiting BACH1." (PMID 34439295, 2021). "Interestingly, cooperation between Nrf2 and Bach1 has been proposed in lung cancer metastatization." (PMID 33805928, 2021). "The transcription factor BACH1 could activate HK-2 transcription and increase glucose uptake, glycolytic rate, and lactate secretion, thereby stimulating glycolysis-dependent metastasis of human lung cancer cells." (PMID 32489324, 2020). "BACH1 is highly expressed and is responsible for metastasis in several cancers, including TNBC, lung cancer, and pancreatic cancer." (PMID 40263598, 2025). "From the validated three gene signature we focused on the two newly identified BACH1 target genes, HTRA3 and ZNF469, both of which are highly induced by BACH1 depletion in lung cancer cells." (PMID 40716152, 2025). "Maf proteins, in complex with BACH1 and 2 are also involved in activating EMT in breast and lung cancer." (PMID 40099944, 2025). "In lung cancer, NRF2 activation leads to the stabilization of BACH1 by inducing HO1, the enzyme responsible for heme breakdown." (PMID 40507333, 2025). "To test this, we used the well-validated KEAP1 inhibitors SFN, CDDO and KI-696, the BACH1 inhibitor TBE56 and the dual KEAP1/BACH1 inhibitor CDDO-TFEA in the lung cancer cell line H1299." (PMID 40716152, 2025). "BACH1 is able to activate the transcription of Hexokinase 2 and GAPDH and thereby promotes lung cancer metastasis." (PMID 38818308, 2024). "Conversely, in a KRAS-driven lung cancer model, long-term supplementation with NAC and vitamin E has been demonstrated to promote metastasis and has been attributed to the stabilization of BACH1 and a metabolic shift in invasive cancer cells." (PMID 38247494, 2024). "BACH1 can activate CD44, and MAPK signalling in lung cancer stem cells (CSCs) and stimulate lung cancer metastasis; its loss represses metastasis in xenograft models." (PMID 37963558, 2023). "NRF2 promotes BACH1 accumulation by inhibiting the heme- and FBXO22-mediated degradation of BACH1 in lung cancer." (PMID 35154476, 2022). "Human metastatic lung cancer has high levels of HO1 and Bach1; thus, HO1 inhibitors represent an effective therapeutic strategy to prevent lung cancer metastasis." (PMID 36163484, 2022). "To test the relevance of the BACH1 nuclear reduction mediated by CDDO-Me and CDDO-TFEA we used an in vitro model of lung cancer cell invasion." (PMID 35313207, 2022). "However, the detailed function of Bach1 in lung cancer stem cells remains unclear." (PMID 34949193, 2021). "The antioxidant supplementation of N-acetyl cysteine and vitamin E mimics the NRF2-HMOX-1 action, leading to the BACH1 stabilization and glycolysis induction in KRAS-mutant lung cancer." (PMID 33228209, 2020). "Activated BACH1 increases the transactivation of glycolysis genes such as Hexokinase 2 and Gapdh which stimulates the KRAS-driven lung cancer metastasis." (PMID 31884422, 2019).
lung cancer (continued). "BACH1 suppresses mitochondrial activity by reprogramming the glucose utilization into glycolytic metabolism via upregulating the transcription of glycolytic genes, including HK2 and GAPDH, in lung cancer cells." (PMID 40263598, 2025). "We chose the lung cancer cell line H1299 for these experiments due to its high BACH1 levels and functional KEAP1 (leading to low NRF2 levels), making it an ideal model for studying both BACH1 and KEAP1 depletion." (PMID 40716152, 2025). "Altogether, our findings demonstrate that our BACH1 signature successfully identified paeoniflorin as a novel BACH1 “inhibitor”, revealing its ability to promote BACH1 degradation via FBXO22 and to suppress lung cancer cell invasion in a FBXO22-BACH1 dependent manner." (PMID 40716152, 2025). "BACH1 activates the transcription of glycolytic enzymes hexokinase 2 (HK2) and GAPDH, thus increasing glucose uptake, glycolysis rates, and lactate secretion to promote KRAS-driven lung cancer metastasis." (PMID 39061897, 2024). "Given that FBXO22 mediates the hemin-induced degradation of BACH1 in lung cancer cells, we assessed whether FBXO22 facilitates BACH1 degradation in MLLr AML cells." (PMID 36774506, 2023). "Recent studies revealed that lowering oxidative stress in lung cancer cells with N-acetylcysteine (NAC) or vitamin E (VitE), or by activating NRF2 reduces ROS and heme levels, which stabilizes BACH1 and activates the transcription of prometastatic genes including HK2 and GAPDH." (PMID 37651203, 2023). "Moreover, BACH1, which binds to ARE binding sites and competes with NFE2L2/NRF2, is required for metastasis in triple negative breast cancer and in lung cancer." (PMID 33499022, 2021). "Antioxidant-treated lung cancer cells showed higher glycolysis rates than control cells that are assessed by ECAR, OCR, increased glucose consumption, and increased lactate production in a BACH1-dependent manner." (PMID 33809182, 2021). "To further evaluate the role of Bach1 in OSA-deteriorated lung cancers, we compared the expression levels of Bach1 in lung cancer nodules and NSCLC cells between CIH and Nor conditions." (PMID 33596919, 2021). "However, increased angiogenesis was also observed in lung cancer cells after antioxidant treatment, for the reduced ROS increases BACH1 expression and promotes angiogenesis independent of HIF-1α, but rather in a BACH1-dependent manner." (PMID 40847302, 2025). "However, there is no direct evidence of BACH1 expression in relation to the prognosis of early-stage lung cancer." (PMID 35035660, 2022). "Interestingly, recent studies have provided compelling evidence that antioxidants accelerate progression and metastasis of lung cancer by stabilization of the transcription factor BTB and CNC homology 1 (BACH1), which has also been identified as a master regulator of breast cancer bone metastasis." (PMID 34039348, 2021). "Furthermore, we found that Bach1 can promote lung cancer stem cell phenotypes in our previous research (has not been published)." (PMID 33596919, 2021). "Moreover, they revealed that BACH1 activates the transcription of Hexokinase 2 and GAPDH and increases glucose uptake ability, glycolysis rates, and lactate secretion, resulting in glycolysis-dependent metastasis of lung cancer cells." (PMID 33324555, 2020). "Furthermore, BACH1 activates the transcription of HK2 (Hexokinase 2) and GAPDH (glyceraldehyde-3-phosphate dehydrogenase), enhancing glucose uptake, glycolytic flux, and lactate secretion, thereby promoting lung cancer metastasis through a glycolysis-dependent pathway." (PMID 40847302, 2025). "However, our data show that in our system HTRA3 induction is necessary but not sufficient for the anti-migratory effect observed in lung cancer cells upon BACH1-depletion, suggesting that BACH1 likely regulates migration through a multifactorial mechanism involving additional targets." (PMID 40716152, 2025).